SPANXN3 (SPANX family member N3)
Synonyms: SPANX-N3; CT11.8
Tractability: No criterion of Open Targets' tractability assessment is met for any kind of drug.
Gene: Protein-coding gene on chromosome X (143,508,735 to 143,517,475, reverse strand). Ensembl gene ENSG00000189252.
Subcellular location (Human Protein Atlas): Nucleoplasm; Nucleoli fibrillar center
Gene Ontology:
Molecular function: protein binding
Homologues: Orthologues: chimpanzee SPANXN3 (91% identical). Paralogues in human: SPANXN2 (77% identical), SPANXN1 (38% identical), SPANXN4 (37% identical), SPANXN5 (36% identical).
Diseases named in the same sentence as SPANXN3 in open-access papers:
SPANXN3 is named in the same sentence as 2 diseases in open-access papers, as found by Europe PMC text mining. Sharing a sentence is not in itself a finding about the gene and the disease. The quoted sentences say what the papers report.
cancer (2 papers, 2019 to 2022). A tumor composed of atypical neoplastic, often pleomorphic cells that invade other tissues. "Investigating non-mutated cancer/testis antigens only identified one peptide from each of two cancer/testis antigens (FAM46D, SPANXN3)." (PMID 31735170, 2019).
SPANXN3 also shares sentences with these, for which no sentence is quoted: tumor (1 paper).